ALKBH5 (alkB homolog 5, RNA demethylase)
Diseases named in the same sentence as ALKBH5 in open-access papers (continued):
Sharing a sentence is not in itself a finding about the gene and the disease.
tumor (continued). "The immunohistochemistry results demonstrated that the positive expression of Ki67, NANOG, OCT4, and SOX2 was increased in the tumor tissues of mice following ALKBH5 overexpression, the effect of which was reversed by the silencing of UBE2C." (PMID 36551544, 2022). "The normalized expression (NX) levels of ALKBH5 were analyzed in various tumor tissues and their corresponding adjacent normal tissues as well as various tumor cells and the corresponding non-tumor cells in The Human Protein Atlas (THPA) database." (PMID 35444654, 2022). "We discovered that ALKBH5 was lowly expressed in GC tumor samples and it significantly decreased the OS of GC." (PMID 36686788, 2022). "As an illustration, both in vitro and in vivo tumor growth is inhibited by silencing of the m6A demethylase alkB homolog 5 RNA demethylase (ALKBH5)." (PMID 35978886, 2022). "The tumor volume and weight of oe-ALKBH5 + sh-NC-treated mice were increased but opposite results were noted in the presence of oe-ALKBH5 + sh-UBE2C, suggesting that the tumor-promoting effect of ALKBH5 can be partially reversed by the silencing of UBE2C." (PMID 36551544, 2022). "In conclusion, we found that BP can inhibit AML cell proliferation and tumor growth by downregulating ALKBH5 to repress m6A demethylation of MLST8/EIF4EBP1 mRNA." (PMID 35579750, 2022). "We showed that knockdown of ALKBH5 expression inhibited tumor growth and weight, while overexpression promoted tumor growth." (PMID 35395767, 2022). "The pan-cancer patient datasets were analyzed to determine the relationship between ALKBH5 expression, genetic alterations, methylation status, and tumor immunity." (PMID 35444654, 2022). "Another m6A demethylase, ALKBH5, was identified as promoting the proliferation of tumor cells and mouse cardiomyocytes." (PMID 35327170, 2022). "Several previous studies have reported contradictory results regarding ALKBH5, suggesting that it acts as either an oncogenic factor or a tumor suppressor in NSCLC." (PMID 35318440, 2022). "Given the tumor suppressive role of ALKBH5 in a small number of cancers, activators of ALKBH5 are needed in such cases." (PMID 35063010, 2022). "Silencing the m6A demethylase alkB homolog 5, RNA demethylase (ALKBH5) suppresses tumor progression in vitro and in vivo." (PMID 35395767, 2022). "illustrated that in CRC, ALKBH5 was downregulated and repressed tumour cell invasion in vitro and in vivo." (PMID 35979628, 2022). "IHC staining results indicated that the deletion of ALKBH5 significantly increased the number of tumor-infiltrating CD3+, CD4+, and CD8+ T cells but not in the FOXP3+ cells." (PMID 36566230, 2022). "We analyzed TCGA and ICGC, the two most authoritative tumor databases, and found that the mRNA expression of ALKBH5 was upregulated in HCC." (PMID 35982895, 2022). "Clinical characterization also revealed that ALKBH5 was closely related to tumor stage and pathological lymph nodes." (PMID 35114989, 2022). "ALKBH5 was the only regulator whose expression was lower in tumor samples than that in normal samples." (PMID 36686788, 2022). "Functionally, the downregulation of ALKBH5 promotes tumor cell death and suppresses the growth of MM cells in vitro, exerting a tumorigenic effect." (PMID 35053496, 2022). "Based on the effect of ALKBH5 on OS and its possible role in tumor suppression and carbohydrate metabolism, we next aimed to explore the role of glucometabolic dysregulation in NB." (PMID 35517412, 2022). "In summary, we discovered a novel ALKBH5/RIG-I/IFNα axis that promotes tumor progression by escaping immune killing mediated by the m6A-dependent HNRNPC binding of DDX58 mRNA in HNSCC." (PMID 35395767, 2022). "ALKBH5 regulates the composition of tumor-infiltrating Tregs and MDSCs by affecting Mct4/Slc16a3 expression in TME, ultimately achieving enhanced immunosuppressive effects and promoting melanoma escape." (PMID 35794625, 2022).
tumor (continued). "ALKBH5 has been identified as m6A demethylase that facilitates tumor cell proliferation, and a correlation between ALKBH5 and poor prognosis of ESCC patients has been illustrated." (PMID 35069736, 2022). "We next examined METTL3 and ALKBH5 expressions in the specimens with a tumor/adjacent tissue global m6A ratio of more than 1.5." (PMID 35078505, 2022). "ALKBH5 plays a dual role as a carcinogen and tumor suppressor in different cancers and, in certain cases, in the same type of cancer." (PMID 35945641, 2022). "ALKBH5 exerts tumor-suppressive effects via the demethylation of the lncRNA KCNK15-AS1, controlling KCNK15-AS1-dependent cell migration and invasion in PC." (PMID 35063010, 2022). "Coinciding with our model, the protein level of ALKBH5 in tumor tissues was lower than that in normal tissues, and some tumor suppressor genes were down expressed when ALKBH5 was knocked down." (PMID 36686788, 2022). "Previous studies showed that the expression of m6A writers (METTL3, RBM15, WTAP), eraser (FTO, ALKBH5) and reader (YTHDF3, YTHDC2) was associated with pathological stage, tumor stage, andprognosis of patients with GC." (PMID 35977935, 2022). "The number of tumor-infiltrating lymphocytes in C3H immunocompetent mice is reduced by ALKBH5 overexpression and restored by IFNα administration." (PMID 35395767, 2022). "In renal cell carcinoma, hypoxia-induced HIF-1α enhances ALKBH5 expression, which, in turn, promotes tumor proliferation through increasing the percentage of cells in the G2/M phase." (PMID 35794625, 2022). "ALKBH5 plays a role in regulating the tumor immune microenvironment and the effect of immunotherapy." (PMID 35945641, 2022). "ALKBH5 can regulate various tumor biological processes, such as the cell proliferation, invasion, migration, metastasis, cancer stem cell self-renewal and tumor microenvironment." (PMID 35784761, 2022). "The result showed that compared with the normal tissues, the tumor tissues in GC patients had a higher expression of m6A modification genes (except ALKBH5)." (PMID 35433701, 2022). "We also found that knocking out ALKBH5 activates the immune system with more antitumor-associated cytokines (IFN-γ, IL-2) and fewer pro-tumor-associated cytokines (IL-10, IL-13)." (PMID 36566230, 2022). "Following these possible reasons and examples, it remains difficult to tell clearly what natural cellular contexts allow ALKBH5 to act as an oncogene or tumor-suppressor." (PMID 35063010, 2022). "Finally, we checked the expression levels of ALKBH5 between GC tumor tissues and adjacent normal tissues with immunohistochemistry (IHC) and the relative expression levels of genes used to construct the risk model when ALKBH5 was knocked down with real-time quantitative PCR (RT-qPCR)." (PMID 36686788, 2022). "We found that overexpression of ALKBH5 increased the tumor size and weight, which were inhibited by RIG-I expression." (PMID 35395767, 2022). "Still, exploring the biological processes of ALKBH5 in tumorigenesis or tumor progression through intrinsic regulation of tumor cells or the remodeling of the tumor microenvironment is of great value." (PMID 36566230, 2022). "ALKBH5 targets Mct4 to suppress MDSCs expansion and lactate levels which directly affects the recruitment of MDSCs in tumor sites." (PMID 36439186, 2022). "From the TCGA HNSCC dataset, it can be seen that the two m6A demethylases are expressed at significantly higher levels in tumor samples than in normal control samples, while ALKBH5 has relatively high abundance in HNSCC." (PMID 35395767, 2022).
tumor (continued). "Overall, METTL3, METTL14, VIRMA, and ALKBH5 immunoexpression levels differed significantly between tumor and normal tissues." (PMID 35048498, 2022). "We discovered that, compared with adjacent normal tissues, ALKBH5 was significantly reduced in tumour tissues in TCGA‐CRC cohort." (PMID 35979628, 2022). "We found that tumour growth rate was faster, and tumour volume and weight were increased when ALKBH5‐knock‐down LOVO cells were implanted (n = 5)." (PMID 35979628, 2022). "After realizing the different expression levels of ALKBH5 between tumor samples and normal samples, we first paid attention to it." (PMID 36686788, 2022). "Then, Cox regression analyses demonstrated that tumor grade, chemotherapy, IDH mutation status, 1p/19q codeletion, and ALKBH5 mRNA expression levels were independent prognostic predictors based on the CGGA_325 combined with CGGA_693 dataset." (PMID 35444654, 2022). "High expression 45 of ALKBH5 in HCC tissues was significantly correlated with tumor size (P= 0.0014) and TNM stage (P= 0.0157)." (PMID 35982895, 2022). "Western blot assay demonstrated that the downregulation of ALKBH5 reduced the expression of the tumor metastasis-related proteins matrix metallopeptidase 2 (MMP2), MMP7, and MMP9 in UM cells." (PMID 33428593, 2021). "ALKBH5 inhibits tumor motility and stemness by demethylating TIMP3, LncRNA NEAT1, WIF1, and LncRNA KCNK15-AS1." (PMID 33428593, 2021). "For instance, several studies found that ALKBH5, a demethylase, plays distinct roles in different tumor types." (PMID 34248650, 2021). "In NSCLC, ALKBH5 was found to decrease tumor growth, invasiveness and metastasis by decreasing m6A-mediated YAP expression and inactivation." (PMID 33814008, 2021). "ALKBH5 expression in tumor cells exhibited a positive correlation with OS time in patients with PDAC." (PMID 34733841, 2021). "The results showed that the downregulation of ALKBH5 significantly suppressed tumor growth, as reflected by the tumor volumes and weight compared with tumors derived from control cells." (PMID 33428593, 2021). "In pancreatic cancer, ALKBH5 acts as a tumor suppressor by decreasing WIF-1 RNA methylation and suppressing the Wnt pathway." (PMID 34094986, 2021). "Demethylase ALKBH5 has been uncovered to exert effects on tumor proliferation, invasion, and metastasis in lung cancer, gastric cancer, pancreatic cancer, colon cancer, glioblastoma, osteosarcoma, and ovarian cancer as an oncogene or tumor suppressor." (PMID 34482808, 2021). "The tumor size, tumor volume, and tumor weight were noticeably larger in tumors induced by vector-expressing cells compared with those induced by ALKBH5-expressing cells." (PMID 34491904, 2021). "ALKBH5 plays an oncogene that Promotes GSCs proliferation and tumor progression by positively regulating FOXM1 in GBM." (PMID 34521394, 2021). "To study the effect of ALKBH5 on UM tumor progression in vivo, we used two short hairpin RNAs (shALKBH5#1 and shALKBH5#2) to decrease ALKBH5 expression." (PMID 33428593, 2021). "Similar to other m6A regulators, ALKBH5 has been demonstrated to have a tumour suppressive role in other tumours." (PMID 33461542, 2021). "ALKBH5 overexpression reduces PC cell proliferation, migration, and invasion and tumour growth, while ALKBH5 deletion promotes the progression of PC." (PMID 34246319, 2021). "The T classification data revealed downregulated ALKBH5 in large-sized tumors, indicating an essential function of ALKBH5 in tumor growth." (PMID 34491904, 2021). "Because EMT has been found to be a key process in tumor metastasis, we investigated the relationship between ALKBH5 and EMT in UM." (PMID 33428593, 2021).
tumor (continued). "IHC assay further confirmed that ALKBH5 was mainly stained in the nuclei of tumor cells and there was the highest expression of ALKBH5 in tumor cells compared with moderate expression in the peritumor tissues and the negative staining in normal liver tissues." (PMID 34112124, 2021). "Specifically, YTHDF1, IGF2BP2, KIAA1429, RBM15, IGF2BP1, ZC3H13, and METTL3 were significantly up-regulated in tumor tissues by unpaired T-tests (P < 0.05), while ALKBH5, YTHDC2, and METTL14 were significantly down-regulated (P < 0.01)." (PMID 34149792, 2021). "Functionally, the proliferation and migration arrays in vitro and in vivo suggest the tumor promoting role of the highly expressed ALKBH5 in HCC." (PMID 34112124, 2021). "Recent studies have revealed m6A methylation components can act as tumor-associated factors, including “writers” (METTL3/14, WTAP and KIAA1429), “erasers” (FTO and ALKBH5), and “readers” (YTHDF1/2/3, HNRNPA2B1, BCDIN3D)." (PMID 33791305, 2021). "Growing evidence has demonstrated that m6A modification is closely associated with tumorigenesis, tumor differentiation, tumor proliferation, tumor invasion and worse survival in BC patients, including METTL3, METTL14, WTAP, ALKBH5, IGF2BP2, IGF2BP3, and FTO." (PMID 33926554, 2021). "Recently, peripheral blood m6A modifier seems to be a potential noninvasive biomarker for the detection and diagnosis of NSCLC, and down-regulating FTO and ALKBH5 in NSCLC had a great connection with tumor stage and metastasis." (PMID 34345203, 2021). "Correspondingly, transwell assay showed that ALKBH5 supported tumor’s migration ability of both HepG2 and HepG2.2.15 cells." (PMID 34112124, 2021). "Mechanistically, ALKBH5 acts as a tumor suppressor by inhibiting LY6/PLAUR Domain Containing 1 (LYPD1) via a m6A-dependent manner in HCC cells." (PMID 33790968, 2021). "ALKBH5 functions differently in specific cancers, as an oncogenic or tumor suppressor by mediating specific mechanisms." (PMID 33790968, 2021). "For example, HIF-dependent ALKBH5 expression mediates enrichment of BCSCs in the hypoxic tumor microenvironment." (PMID 33469161, 2021). "We identified ALKBH5 as a tumor suppressor, whose expression was dramatically diminished in human ESCC clinical specimens." (PMID 34491904, 2021). "ALKBH5 has been identified as a tumour suppressor in HCC that can inhibit its proliferation and invasion." (PMID 34246319, 2021). "Taken together, ALKBH5 is playing a crucial role in promoting tumour metastasis, and therefore intracellular silencing of ALKBH5 in the TME would hold the potential to control tumor metastasis via increasing the efficacy to anti-PD-1 therapeutics." (PMID 34571899, 2021). "ALKBH5 alteration in tumor cell modulating its lactate content affects the tumor infiltration of Tregs and myeloid-derived suppressor cells (MDSCs) in TME, which are notorious immunosuppressants in anti-tumor immunity." (PMID 34526985, 2021). "Consistently, animal studies showed that ALKBH5 overexpression promoted EOC tumor growth and resistance to cisplatin in vivo." (PMID 34496932, 2021). "We further use a tissue microarray including another 79 pairs of tumor and peri-tumor from Chinese HBV-HCC patients to assert the ALKBH5 expression pattern." (PMID 34112124, 2021). "ALKBH5 can affect the lactic acid content of the tumor microenvironment, tumor-infiltrating Tregs, and myeloid-derived suppressor cells by regulating the expression and splicing of target genes." (PMID 34745261, 2021). "In melanoma and colorectal cancer, ALKBH5 produces high levels of lactic acid in the tumor microenvironment (TME) and promotes the infiltration of tumor-infiltrating Tregs and myeloid-derived suppressor cells." (PMID 34531875, 2021). "The mechanism was that ALKBH5 modulated Mct4/Slc16a3 expression, regulated lactate content of the tumor microenvironment, and adjusted the composition of tumor-infiltrating Treg cells and myeloid-derived suppressor cells." (PMID 34345203, 2021).
tumor (continued). "We found that ALKBH5 was downregulated in the PDAC tumor cells and served as an independent, favorable prognostic marker." (PMID 34733841, 2021). "115/159 of Fudan HBV-HCC samples displayed a higher ALKBH5 mRNA level, 96/159 for higher ALKBH5 protein level, in tumor compared to paired peri-tumor tissues and there were significant differences by paired t test." (PMID 34112124, 2021). "These functions result in ALKBH5 inhibition of tumor growth and metastasis by reducing the expression and activity of YAP in vivo." (PMID 32106857, 2020). "The m6A eraser ALKBH5 has been shown to act as both a tumor suppressor and promoter, and has the ability to demethylate m6A on single-stranded RNA and DNA." (PMID 32911345, 2020). "ALKBH5 regulated cancer cell proliferation, migration, invasion, tumor progression, metastasis, tumorigenesis and chemoresistance through modulating m6A methylation." (PMID 32742194, 2020). "The suppression of the rates of cell proliferation and invasion indicated a PER1-dependent anti-tumour function of ALKBH5 in PC progression." (PMID 32429928, 2020). "At present, little has been unravelled about the mechanism through which ALKBH5 functions in tumour genesis and development." (PMID 32329191, 2020). "Further, ALKBH5 inhibited tumor growth and metastasis in vivo by reducing the expression and activity of YAP." (PMID 32106857, 2020). "Overexpression of ALKBH5 reduced tumoural proliferative, migrative, invasive activities in vitro and ameliorated tumour growth in vivo, whereas ALKBH5 knockdown facilitated PC progression." (PMID 32429928, 2020). "In fact, the depletion of ALKBH5 in GSCs reduced their self-renewal and proliferation, and impaired their ability to form a tumour." (PMID 32316617, 2020). "Compared with the control groups, mice with ALKBH5 overexpression in 143B cells exhibited a significant promotion of tumor growth in vivo." (PMID 32021563, 2020). "When compared to PC cells with low-level ALKBH5 expression (BxPC-3/vector group, SW1990/shALKBH5 group), we found a dramatically decreased tumour volume in groups of the BxPC-3/Lv-ALKBH5 and SW1990/scramble." (PMID 32429928, 2020). "Serving as the key demethylase of m6A modification, ALKBH5 acts to promote the tumour progression by maintaining the stemness of breast cancer cells." (PMID 32429928, 2020). "Overexpression of ALKBH5 reduces the cell proliferation, migration, invasion and tumour growth of PC, whereas ALKBH5 knockdown facilitates PC progression." (PMID 32429928, 2020). "Our study reveals that ALKBH5, characterized as a tumor suppressor, attenuates the expression of LYPD1 via an m6A-dependent manner in HCC cells." (PMID 32772918, 2020). "On the contrary, ALKBH5 overexpression retarded tumor growth with considerably diminished tumor volumes and weights." (PMID 32772918, 2020). "ALKBH5 plays a dual role in various cancers through regulating kinds of biological processes, such as proliferation, migration, invasion, metastasis and tumor growth." (PMID 32742194, 2020). "We here aimed to explore the mechanism whereby ALKBH5 inhibits tumor growth and metastasis by regulating the expression and activity of YAP in NSCLC." (PMID 32106857, 2020). "The presented findings suggest m6A demethylase ALKBH5 inhibits tumor growth and metastasis by reducing YTHDFs-mediated YAP expression and inhibiting miR-107/LATS2–mediated YAP activity in NSCLC." (PMID 32106857, 2020). "We found that YAP expression was negatively correlated with ALKBH5 expression in NSCLC tumor tissues." (PMID 32106857, 2020). "As a tumor suppressor, ALKBH5 is significantly downregulated in PAC, and its expression is related to patient survival, as well as being an independent marker of prognosis." (PMID 32911345, 2020).